CCR6 (C-C motif chemokine receptor 6)
Diseases named in the same sentence as CCR6 in open-access papers (continued):
Sharing a sentence is not in itself a finding about the gene and the disease.
autoimmune disease (continued). "Nonetheless, the novel finding in this study that 1,25(OH)2D3-treated memory CCR6+ Th cells retain their suppressive capacity in synovial fluid suggests that these cells may have therapeutic value in autoimmune diseases such as RA." (PMID 31379807, 2019). "Finally, CCR6 and its ligand CCL20 (MCP-3α) coordinate regulation of effective humoral responses also have been linked to autoantibody-driven autoimmune diseases including lupus." (PMID 31921124, 2019). "When CCL20 binds to its receptor CCR6, it not only participates in regulating the immune homeostasis of the body, but also serves to modulate the inflammatory response through the Th17 pathway, playing an essential role in the progression of autoimmune diseases and various malignant tumors." (PMID 35702353, 2022). "Moreover, CSE-induced premature senescence of CCR6+Th17 is associated with VEGFα production, which could confer pathogenicity to CCR6+Th17 cells and contribute to worsen chronic inflammation in smokers with autoimmune diseases when homing to mucosal tissues." (PMID 32300208, 2020). "Therefore, we propose that dual targeting of CXCR3 and CCR6 with a fully humanized BsAb may display a potent interventional approach for the treatment of inflammatory and autoimmune diseases." (PMID 28873441, 2017). "Homeostasis disruption of CCR6/CCL20 axis plays a critical role in inflammation and autoimmune diseases, suggesting the potential of CCR6 as therapeutic target for patient treatment." (PMID 34225700, 2021). "This autoimmune disease is characterized by the increased release of CCL20 and the buildup of CCR6 bearing mononuclear T cells in the joints." (PMID 30004409, 2018). "As the CCR6 gene and loci close to CCR6 have been proven to be associated with a number of autoimmune diseases, we examined whether there was an association of this gene with VKH syndrome, a well known autoimmune disease involving the eye, the neurologic/auditory and integument organs." (PMID 23935994, 2013). "As with other autoimmune diseases, AS patients exhibit an imbalance of CCR4+CCR6+ helper T cells and regulatory T cells." (PMID 23637848, 2013). "Both CCR6 and CXCR3 play an important role in the recruitment of CD4+ T cells in many autoimmune diseases." (PMID 24223818, 2013). "Both CCR6 and CXCR3 expressing CD4+ T cells have been identified in the synovial fluid of rheumatoid arthritis patients as well as in tissue samples of patients with other autoimmune diseases, such as multiple sclerosis." (PMID 27467144, 2016). "This study reports that Activin A, a protein abundantly produced in the skin during normal and pathological wound healing and inflammatory/autoimmune diseases (this study), induces the differentiation of human CD14+ monocytes in Langerin+, Birbeck granules+, E-cadherin+, CLA+ and CCR6+ cells." (PMID 18813341, 2008). "Furthermore, a gene such as CCR6 (MIM: 601835) could have been missed if locus-specific TALEN gene editing evidence in this locus had not been considered, as there is no reported statistical colocalization between the CCR6 eQTLs and autoimmune-disease GWASs." (PMID 33798443, 2021). "In autoimmune disease, expansion of the CD146-enriched IL-17+ T cell population has been reported, while no or very low correlation between IL-17 and CCR6, CD161, or CCR2 was found." (PMID 30912766, 2019).
rheumatoid arthritis (51 papers, 2005 to 2026). A chronic, systemic autoimmune disorder characterized by inflammation in the synovial membranes and articular surfaces. "Rheumatoid arthritis (RA) is a severe chronic systemic inflammatory disease that causes joint destruction, and CCR6 expression contributes to Th17 cell function in the disease." (PMID 37092451, 2023). "In other autoimmune diseases, such as rheumatoid arthritis (RA) and multiple sclerosis, differences in frequencies of CCR6+ memory Th cells were associated with a clinical phenotype or disease stage." (PMID 35045868, 2022). "A rheumatoid arthritis GWAS in Japanese identified CCR6 rs3093024 as the causal variant associated with the CCR6 expression." (PMID 33717080, 2021). "Genetic associations have been identified between CCR6 polymorphisms and immune system disorders in humans including rheumatoid arthritis (RA) and Crohn’s disease." (PMID 32922257, 2020). "Very recently, it was shown that the frequency of TH17 cells (CCR6+) in rheumatoid arthritis (RA) patients is associated with anti-citrullinated protein antibodies (ACPA) status." (PMID 28615072, 2017). "The non-coding triallelic dinucleotide polymorphism CCR6DNP is associated with risk for rheumatoid arthritis, and is considered likely causal because allelic variation correlates with expression of the chemokine receptor CCR6." (PMID 27626929, 2016). "Th17 cells play a pivotal pathogenic role in mouse models of human rheumatoid arthritis, multiple sclerosis and in patients with Crohn disease, in which CCR6 is crucial for Th17 cell attraction to sites of inflammation." (PMID 20668702, 2010). "In addition to support for this factor coming from the rheumatoid arthritis risk variant CCR6DNP regulating CCR6 via PARP-1, it is interesting to note that a recent age at menopause GWAS linked the loci found in that effort to DNA damage response genes." (PMID 29392078, 2018). "Previously, a dual nucleotide polymorphism within the first intron of CCR6 (termed the CCR6DNP) had been associated with risk for rheumatoid arthritis, but the pathway by which this variant altered gene expression could not be determined." (PMID 27626929, 2016). "Recent studies have suggested that CCR6 polymorphisms are associated with an increased risk for a variety of autoimmune- or immune-mediated diseases, such as rheumatoid arthritis (RA), Crohn’s disease, systemic sclerosis (SSc) and vitiligo." (PMID 25928629, 2015). "Notable examples include D2HGDH in lung tissue for asthma, CYBRD1 in breast mammary tissue for breast cancer, and CCR6 in spleen tissue for rheumatoid arthritis." (PMID 42201988, 2026). "RANK and CCR6 expressed on monocytes are targets for the regulation of bone resorption in rheumatoid arthritis and osteoporosis." (PMID 36891058, 2023). "Around 3% of circulatory monocytes expressed CCR6 in blood and synovial fluid from rheumatoid arthritis patients and these monocytes responded to CCL20 chemotaxis in vitro." (PMID 33679793, 2021). "Based on the differential expression of CCR6 on Th cells, recent studies have indicated their potential proinflammatory role in the development of autoimmune disorders, including rheumatoid arthritis." (PMID 29441231, 2018). "It is important to note that autoimmune, CCR6-expressing, B cells also play an important role in the pathology of both multiple sclerosis and rheumatoid arthritis." (PMID 27336468, 2016). "The ligand-receptor pair MIP-3α-CCR6 is responsible for the chemoattraction of immature dendritic cells, effector/memory T cells and B cells, and plays a critical role in cancer and rheumatoid arthritis." (PMID 25013520, 2014). "In vivo, a chemotactic effect of the CCL20/CCR6 axis has been demonstrated in diseases such as rheumatoid arthritis and autoimmune encephalitis." (PMID 24699535, 2014).
rheumatoid arthritis (continued). "Previous reports have stated that, in a mouse model of rheumatoid arthritis, the addition of anti-CCR6 monoclonal antibodies inhibited the trafficking of Th17 cells to the arthritic joint and impeded early disease development." (PMID 23823618, 2013). "Furthermore, the functional CCR6DNP affects CCR6 transcription in rheumatoid arthritis, systemic sclerosis, and Crohn's diseases." (PMID 33717080, 2021). "Interestingly, a recent study also showed that the rheumatoid arthritis GWAS-implicated risk variant, CCR6DNP, regulates CCR6 via PARP-1." (PMID 29392078, 2018). "CCR6 expression is of critical importance for Th17 migration and has been associated with aggravated experimental glomerulonephritis, graft-versus-host disease (GVHD), inflammatory bowel disease and rheumatoid arthritis." (PMID 23717673, 2013). "As CCR6 is expressed on many cell types that drive the inflammatory process in rheumatoid arthritis (RA), we also addressed the role of CCR6 in an additional arthritis model, the human TNF transgenic mouse model." (PMID 30133119, 2018). "Previous studies in patients with rheumatoid arthritis and juvenile idiopathic arthritis in an animal model have reported the presence of T cells expressing CXCR3 and CCR6 in synovial tissues." (PMID 35924250, 2022). "In rheumatoid arthritis, the CD4+CXCR3+CCR6+ subset is known to express high levels of IFNγ with poor secretion of IL-17A,36 though we did not observe any associated cytokine profile in our remission patients." (PMID 31540934, 2019). "Non-classical CD161+CCR6+ Th1 lymphocytes of rheumatoid arthritis patients, unlike classical CD161-CCR6- Th1 cells, are reprogrammed into pathogenic Th17 lymphocytes in Th17-inducing conditions, which may contribute to their pathogenicity during the course of rheumatoid arthritis." (PMID 38022605, 2023). "Likewise, for TH22/TH17 autoimmune ailments such as rheumatoid arthritis, the application of CCR10 or CCR6 antagonists offers promise in disease management." (PMID 37760825, 2023). "Memory CCR6+ Th cells, excluding Tregs, were sorted from healthy controls or treatment-naïve patients with early rheumatoid arthritis (RA) and cultured with or without 1,25(OH)2D3." (PMID 31379807, 2019). "We analyzed proportions of Th1 (CXCR3+), Th17 (CCR6+) and TfH (CXCR5+) cells within the CD4+CD45RO+ activated/memory population of a cross sectional group of seropositive Rheumatoid Arthritis patients on stable therapy (Cohort 1), compared to age and gender-matched healthy controls." (PMID 28004828, 2016). "CCR6 is involved in mucosal humoral immunity and intestinal T cell homing, and it has recently been reported that Th17 cells expressing CCR6 are preferentially recruited to inflamed joints via its ligand CCL20 in an animal model of rheumatoid arthritis." (PMID 18698345, 2008). "However, low level of CCR6 expression has been reported on myeloid blasts from the peripheral blood of AML patients, and on CD14+ monocytes from peripheral blood and synovial fluid of rheumatoid arthritis patients." (PMID 34277460, 2021). "Indeed, increased levels of CCL20, the chemokine attracting CCR6+ cells, were detected in SpA joints, albeit not as prominent as in rheumatoid arthritis." (PMID 29922283, 2018). "Early studies on the specific blocking of either CCR6 or CCL20 included the transfer of CD4+ T cells from Sakaguchi mice into severe combined immunodeficiency (SCID) mice and the administration of a monoclonal antibody (mAb) against CCR6 in a rheumatoid arthritis model." (PMID 30453514, 2018). "Th17/Th22 (CXCR3−CCR4+), Th17.1 (CXCR3+CCR4−), DP (CXCR3+CCR4+), and DN (CXCR3−CCR4−) CCR6+ memTh, cells sorted from PBMC of healthy donors or treatment-naïve early rheumatoid arthritis (RA) patients, were cocultured with SF from RA patients with or without anti-IL17A, anti-IFNγ, or 1,25(OH)2D3." (PMID 34082814, 2021).
COVID-19 (44 papers, 2020 to 2025). A disease caused by infection with severe acute respiratory syndrome coronavirus 2. "It was shown that the expression of Th17 cell-associated genes (RORC, IL17A, IL17F, and CCR6) was downmodulated in peripheral blood CD4+ T cells in COVID-19 patients." (PMID 37626620, 2023). "This cytokine and its role in COVID-19 has previously been under the scope of our research: we investigated its association with T cellular subsets, as it negatively correlated with the CCR6+ cells in acute COVID-19 patients with the Wuhan variant." (PMID 36430621, 2022). "Similar results were obtained using molecular biological research methods: the expression of Th17-associated genes (RORC, IL17A, IL17F, and CCR6 decreased in the peripheral blood CD4+ T cells from patients with severe COVID-19." (PMID 35632823, 2022). "Conversely, during the acute phase of SARS-CoV-2 infection, CD4+ T cells from the lungs of patients with COVID-19 did not increase Th17-associated genes, including RORC, IL17A, and IL17F, and CCR6 expression was significantly reduced in patients with severe COVID-19." (PMID 36146622, 2022). "Another study showed that the pathogenicity of the COVID-19 cytokine storm was associated with increased numbers of Th 17 and highly proinflammatory CCR6+ CD4+ T cells in COVID-19 patients." (PMID 40236655, 2025). "It was shown that in CD4+ peripheral blood T-lymphocytes of patients with severe COVID-19, there was decreased expression of Th17-associated genes on the example of RORC, IL17A, IL17F and CCR6." (PMID 36674665, 2023). "For instance, lung tissue specimens obtained from COVID-19 patients were enriched for cells co-expressing CCR6 and IL17A and also had high levels of IL-6, IL-17A, GM-CSF, and IFNγ found in BALF." (PMID 38179278, 2023). "Increasing the CXCR3+CCR6− CD8+ T cell (Tc1) level was noted in adenoid tissue from convalescent COVID-19 patients compared to control subjects." (PMID 36146713, 2022). "The lung tissues of patients with COVID-19 were enriched with CCR6 and IL-17A co-expressing cells, and high concentrations of IL-6, IL-17A, GM-CSF, and IFNγ were found in the liquid fraction of BALF." (PMID 35632823, 2022). "Th1 and Th17 are often characterized by CXCR3 and CCR6, respectively, and CXCR3+ and CCR6+ SARS-CoV-2-specific CD4+ T cells were both detected during acute COVID-19." (PMID 35992306, 2022). "Another report showed that peripheral blood of a severe COVID-19 patient had a strikingly high number of CCR6+ Th17 cells." (PMID 33603759, 2021). "Circulating Th and Tfh-like cells expressing CXCR3 (Th1, Tfh1) and/or CCR6 (Th1/17, Tfh1/17 and Th17, Tfh17) showed a trend towards increased activation in patients with active COVID-19." (PMID 34614036, 2021). "During acute COVID-19 CXCR3+CCR6− Tfh1-like cells were decreased and the levels of CXCR3−CCR6+ Tfh17-like were increased then in HC and convalescent patients." (PMID 35723393, 2021). "Th1 cells observed in individuals with COVID-19 demonstrated a distinctive expression of CXCR3 and CCR6, in addition to transcripts encoding cytokines and chemokines with anti-viral properties, such as CD154, IFN-γ, IL-2 (interleukin-2), and TNF (tumor necrosis factor)." (PMID 38675727, 2024). "Finally, a meta2cell enriched in patients with persistent severe COVID-19 at day 13 (metacell C) contains cells that express hallmark TH17 genes (RORC and CCR6), reflecting a shift toward type III inflammation." (PMID 36973557, 2023). "The minimum level of Th17 was observed in patients with severe COVID-19, moreover, within the framework of the general pool of CCR6+ Th17, it was exactly noted in severe patients that there was a decrease in the proportion of CCR4− CXCR3+ Th17.1 cells and an increase in CCR4+ CXCR3—“classical” Th17." (PMID 36674665, 2023). "Moreover, the lung tissues in COVID-19 patients were enriched in CCR6- and IL17A-co-expressing cells." (PMID 37626620, 2023).
COVID-19 (continued). "Moreover, lung tissues collected from COVID-19 patients were enriched in CCR6 and IL-17A co-expressing cells." (PMID 37626620, 2023). "Moreover, CD4+ T cells, co-expressing CCR6 and IL-17A, were detected in lung tissues of patients with COVID-19." (PMID 36012146, 2022). "Additionally, more pro-inflammatory CCR6+ Th17 subsets in the peripheral blood of severe COVID-19 cases than mild COVID-19 cases were reported." (PMID 36069182, 2022). "COVID-19 convalescents had increased CCR6-expressing CD8+ T cells." (PMID 36146713, 2022). "Moreover, CXCR3+CCR6- Tc1 cells were decreased in patients with acute COVID-19 and COVID-19 convalescents, whereas Tc2 and Tc17 levels were increased compared to HC." (PMID 36146713, 2022). "Several studies have reported CCR6+ SARS-CoV-2-specific T cells in convalescent COVID-19 patients, but their durability was unknown." (PMID 35992306, 2022). "Patients with severe COVID-19 demonstrate elevated levels of CCR6+ Th17 cells." (PMID 34127050, 2021). "The data reported by others suggest that peripheral blood of patients recovered after COVID-19 had elevated proportion of CXCR3+CCR6− Tfh1 and CXCR3−CCR6− Tfh2 cells compared with control group, whereas percentage of CXCR3−CCR6+ Tfh17 cells was significantly decreased." (PMID 35723393, 2021). "GM-CSF+ IL-6+ CCR6+ Th17 cells have been detected in the blood of COVID-19 patients." (PMID 35126355, 2021). "Therefore, targeting the CCL20/CCR6 axis could represent a promising future potential therapeutic opportunity for patients with severe COVID-19 who often exhibit elevated levels of Th17 cells." (PMID 40867589, 2025). "Therefore, regulating the CCR6+CD8+T cell subset is a crucial aspect of COVID-19, whereas IL-27 might act as a potential regulator thereof." (PMID 36146713, 2022). "Indeed, elevated levels of CCR6+CD8+ T cells were observed in the BAL fluid in acute COVID-19, which might be due to the chemokine CCL20 being overproduced by alveolar macrophages and other cell types at the site of inflammation." (PMID 36146713, 2022). "Finally, IL-27 negatively correlated with the CCR6+ cells in acute COVID-19 patients." (PMID 36146713, 2022). "Additionally, increased frequencies of virus-specific cTfh cells (CD4+CXCR5+OX40+CD40L+) were observed in acute and convalescent COVID-19 cases, and the frequencies of both SARS-CoV-2-specific cTfh cells and S-specific CCR6+CXCR3-cTfh17 cells were closely associated with low disease severity." (PMID 34603308, 2021). "A shift toward activated Treg subtypes was seen in patients with COVID-19 with increases in the activated CCR4+ (annotated as CCR4+), Helios–CCR6+ effectors, and several groups of proliferating Tregs." (PMID 36669118, 2023). "COVID-19 is characterized by a decreased percentage of T-helper cells bearing the key Th17 surface markers, CD161 and CCR6." (PMID 37626620, 2023). "COVID-19 is also featured with decreased percentage of T-helper cells bearing key surface Th17 cell markers—CD161 and CCR6—compared to control group." (PMID 37626620, 2023). "SARS-CoV-2 maternal infections display higher frequencies of CXCR5+CD4+ and CCR6+CD4+ T cells and higher plasma concentrations of IL-6 and IL-18, when compared with gestational age–matched COVID-19–vaccinated counterparts." (PMID 37490342, 2023). "Other works described LDNs as CD25+CCR6+CD24+CD66b+CD11b+ in asymptomatic pregnant women infected with SARS-CoV-2, and as CD66b+CXCR1+CCR6+ in a cohort of aged individuals with severe COVID-19." (PMID 37444436, 2023). "An abnormal composition of Tfh subsets was also observed in patients with COVID-19, who had an increase in the proportion of CXCR3+CCR6– Tfh1 and CXCR3–CCR6– Tfh2 and a decrease in the level of CXCR3–CCR6+ Tfh17 relative to control group values." (PMID 35216349, 2022).